JAK2 (Janus kinase 2)
Diseases named in the same sentence as JAK2 in open-access papers (continued):
Sharing a sentence is not in itself a finding about the gene and the disease.
Insulin resistance (continued). "IL-6/Jak2 signaling adversely interferes with the action of insulin, resulting in glucose intolerance and insulin resistance." (PMID 34943061, 2021). "While JAK2 and STAT3 were associated with all the noted pathways except insulin resistance and Herpes simplex infection, respectively, only two connections (negative regulation of cell proliferation and insulin resistance) were reported for NOS3." (PMID 33100263, 2020). "Visfatin-induced inflammation and insulin resistance were regulated by JAK2/STAT3 and IKK/NF-κB signaling; together with AG490 or Bay 7082, visfatin significantly reduced mRNA levels of IL-6, TNF-α and IL-1β and rescued insulin signaling." (PMID 31396538, 2019). "In hepatocytes, janus kinase 2/signal transducer and activator of transcription 3 pathway is the main pathway of its action, and leptin is involved in hepatic steatosis and insulin resistance through suppressor of cytokine signaling expression." (PMID 28081181, 2017). "In the present work, mice with myeloid-specific deletion of JAK2 were generated using the lysozyme M (LysM)-Cre line to assess its role in mature macrophages in the pathogenesis of inflammation and insulin resistance." (PMID 28794431, 2017). "However, CXCL5 in insulin-sensitive tissues, such as muscles, mediates insulin resistance through the Jak2/Stat5 signaling pathway." (PMID 40801626, 2025). "CDD may improve ovarian function and insulin resistance in PCOS-IR mice by modulating the IL6/JAK2/STAT3/FOXO4 signaling pathway." (PMID 41573199, 2025). "The JAK2/STAT3 signaling pathway is involved in the development of insulin resistance in patients with T2DM, and its abnormal activation may damage pancreatic beta cells to reduce insulin synthesis." (PMID 40365304, 2025). "As an alternative and complementary therapy, Cangfu Daotan Decoction may improve ovarian function and ameliorate insulin resistance in PCOS mice by modulating the IL6/JAK2/STAT3/FOXO4 signaling pathway." (PMID 41573199, 2025). "In summary, CDD may improve ovarian function and insulin resistance in PCOS mouse by regulating the IL6/JAK2/STAT3/FOXO4 signaling pathway." (PMID 41573199, 2025). "Overall, our results, in line with previously published data, demonstrated that the activation of JAK2 signaling may directly modulate the AKT pathway, thus affecting a crucial pathogenic mechanism responsible for the development of insulin resistance." (PMID 32413585, 2020). "Developing strategies to target macrophage JAK2 could potentially have a beneficial effect in attenuating insulin resistance and inflammation." (PMID 28794431, 2017). "In addition, the RBP4/retinol complex stimulates JAK2/STAT5 signaling and expression of the suppressor of cytokine signaling 3, which is implicated in insulin resistance." (PMID 25479076, 2014). "In addition, Aβ induced insulin resistance by activating the JAK2/STAT3/SOCS-1 signaling pathway." (PMID 37033452, 2023). "Recent reviews also indicate that anthocyanins regulate leptin signaling by increasing ObR receptor expression and activating the JAK2/STAT3 and PI3K/Akt pathways, which improves leptin sensitivity and reduces insulin resistance." (PMID 41374016, 2025). "GP treatment enhanced the expression of JAK2-INSR-IRS2 and Akt in the liver, thereby promoting hepatic insulin signaling and alleviating hepatic glucose production and insulin resistance." (PMID 40869401, 2025). "In our study, CDD effectively improved body weight, insulin resistance index, and ovarian function in PCOS-IR model mice, and significantly downregulated both mRNA and protein expression levels of the IL6/JAK2/STAT3/FOXO4 signaling pathway." (PMID 41573199, 2025). "Egr2 represses the expression of SOCS-1 and the phosphorylation of JAK2 and STAT3 in HepG2 cells following palmitate treatment, and Egr2 upregulation induces insulin resistance in HepG2 cells." (PMID 38396891, 2024).
Insulin resistance (continued). "To investigate the mechanism by which α7nAchR activation prevents insulin resistance, we also evaluated the ability of PNU to prevent insulin resistance after pharmacological inhibition of α7nAchR and its downstream effectors JAK2 and STAT3." (PMID 35883638, 2022). "Clinical data showed an increased phosphorylation of JAK2 and STAT in skeletal muscle biopsies from patients with T2DM and correlate with measures of insulin resistance." (PMID 32413585, 2020). "We first examined the effects of a specific inhibitor of JAK2/STAT3, AG490, and a specific NF-κB inhibitor, BAY11-7082, on the visfatin-induced expression of inflammatory cytokines and insulin resistance in HepG2 cells." (PMID 31396538, 2019). "During high-fat diet (HFD) feeding, macrophage-specific JAK2 knockout (M-JAK2−/−) mice gained less body weight compared to wildtype littermate control (M-JAK2+/+) mice and were protected from HFD-induced systemic insulin resistance." (PMID 28794431, 2017). "Conversely, excessive JAK2 activity may impair this process; hepatocyte-specific JAK2 deletion alleviates HFD-induced steatohepatitis and insulin resistance, while its overactivation suppresses Akt signaling, potentially exacerbating insulin resistance." (PMID 40869401, 2025). "Mechanistically, JAK2 overexpression amplifies the insulin promoter activity, whereas phosphorylated STAT3 impairs the insulin signaling and glucose uptake in skeletal muscle, driving insulin resistance." (PMID 40831950, 2025). "This dual effect—enhancing IRS signaling while reducing JAK2-mediated inflammation—suggests that GP may effectively activate the INSR–IRS2–Akt signaling axis, ultimately improving insulin sensitivity and mitigating insulin resistance." (PMID 40869401, 2025). "Moreover, insulin resistance may directly blunt GH-induced intracellular signaling, as insulin has been shown to downregulate GH receptor (GHR) expression and impair JAK2/STAT5 activation—key pathways for GH-mediated growth promotion." (PMID 41282298, 2025).
leukocytosis (41 papers, 2006 to 2026). "Its inhibition in murine models with JAK2 mutations has proven effective in reducing leukocytosis and splenomegaly." (PMID 40699626, 2025). "ExT clustered with CALR (type-2 more than type-1), TN and MPL, and leukocytosis with JAK2 mutation (p < 0.001)." (PMID 38238287, 2024). "ExT clustered with CALR (type-2 more than type-1) and TN and leukocytosis with JAK2 mutation (p < 0.01)." (PMID 38238303, 2024). "The JAK2 p.V617F mutation status was identified as an independent prognostic factor, which was further associated with leukocytosis." (PMID 39682300, 2024). "It was observed that in patients with PMF, the incidence was comparable to that reported for ET, and was also increased in elderly patients and those with the JAK2 p.V617F mutation with associated leukocytosis." (PMID 39682300, 2024). "Leukocytosis and JAK2 mutation are two risk factors in our study that are also associated with disease progression in MPNs; thus, it is possible that these risk factors contribute to death or CV events through non-cardiovascular etiologies." (PMID 37367089, 2023). "In PMF, JAK2 V617F has been associated with advanced age, higher Hb levels, lower platelet counts, and leukocytosis." (PMID 37444441, 2023). "One study reported that >50% of the JAK2 mutational burden is associated with fibrotic transformation, and leukocytosis is a risk factor for leukemic transformation and survival in PV patients." (PMID 36230834, 2022). "Based on the current study population our results support the idea that leukocytosis and JAK2 positivity are more important risk factors for thrombosis than hemoglobin and platelet values." (PMID 27094255, 2016). "Leukocytosis and JAK2 V617F allele burden have been identified as novel thrombotic risk factors but have not been confirmed as such yet." (PMID 25832853, 2015). "The mechanisms underlying this increased thrombotic risk are not yet fully understood, and the role of risk factors such as JAK2 status and leukocytosis has yet to be conclusively established." (PMID 22084665, 2011). "Additionally, our study identified the potential risk factors for death or CV events in patients with MPN, including leukocytosis, JAK2 mutation, ACS events within 12 months of MPN diagnosis, and prior CVD." (PMID 37367089, 2023). "Leukocytosis and JAK2 positivity are risk factors for thrombosis and may be more important than the elevated hemoglobin levels and platelet counts." (PMID 27094255, 2016). "Leukocytosis and JAK2 mutation are shown to be additional risk factors." (PMID 27094255, 2016). "Furthermore, patients with JAK2 mutations or leukocytosis exhibited higher TLR2 expression." (PMID 39157201, 2024). "Index ACS events within 12 months of MPN diagnosis, leukocytosis at the time of index ACS events, prior CVD, and JAK2 mutations were associated with an increased risk of MACE." (PMID 37367089, 2023). "Our results suggest that patients with MPN who present with ACS and have a history of JAK2 mutation, prior CVD, have recently been diagnosed with MPN, and have leukocytosis at the time of ACS should be monitored closely for adverse cardiac events." (PMID 37367089, 2023). "The CALR-mutated patients had a significantly lower cumulative incidence of developing leukocytosis compared to JAK2 mutant patients (p = 0.004)." (PMID 37444441, 2023). "Of note, this subgroup had lower leukocytosis, JAK2 VAF, and cholesterol levels, along with less smoking history when compared with men." (PMID 33006021, 2021). "JAK2 V617F mutations in PMF are associated with older age, higher HB level, leukocytosis, and lower platelet count." (PMID 33255170, 2020). "In summary, our studies suggest JAK2 inhibition as a novel therapeutic approach to decrease ACD risk associated with excessive myelopoiesis and leukocytosis." (PMID 32086626, 2020). "JAK2 V617F induced striking leukocytosis and neutrophilia in Balb/c mice, but leukocytosis was much milder in B6 recipients." (PMID 17183644, 2006).
leukocytosis (continued). "JAK2 V617F also induced leukocytosis and neutrophilia that was much more prominent in Balb/c mice than in B6." (PMID 17183644, 2006). "Upregulation of those pathways may be explained by leukocytosis, JAK2 activation, or excess of granulocytes reported in PV cases." (PMID 31064135, 2019). "JAK2 V617F induced significant leukocytosis in Balb/c mice, but only a modest increase in B6 mice." (PMID 17183644, 2006). "For non-MPN hematological diseases, four V617F mutations were detected in samples of leukocytosis of unknown origin (4/12), however, no JAK2 V617F mutations were identified in the 10 controls." (PMID 25624900, 2015). "Unlike leukocytosis, the influence of JAK2 V617F on thrombotic risk is not clear." (PMID 25832853, 2015). "In our series, and that of others with abdominal venous thrombosis, leukocytosis was not prevalent, and JAK2 V617F allele burdens implied heterozygosity; therefore, a unique mechanism for thrombosis in this vascular bed exists, and is probably gender associated." (PMID 22084670, 2011). "And, while both IFN-α and HU treatment were found to reduce leukocytosis and neutrophilia, IFN-α was also shown to normalize NLR, lower JAK2 VAF, and better preserve lymphopoiesis." (PMID 41091181, 2025). "All 8 patients with JAK2 fusion genes (PCM1, n = 7; BCR, n = 1; male 7/8; median age 69 years, range 29–73) presented with leukocytosis (median 25.9 × 109/l, range 10.5–55.0)." (PMID 37454239, 2023).
colitis (40 papers, 2012 to 2026). Inflammation of the colon. "Consistent with previous investigations, our results showed that BBR can inhibit inflammatory-associated mediators’ expression by dampening the JAK2/STAT3 signaling activation in cats with DSS-induced colitis." (PMID 36287004, 2022). "While the IL-23-IRE1α/XBP1 pathway in ILC3s may be protective in colitis, other IL-23 targets including JAK2 and TYK2 are pathogenic." (PMID 38722686, 2024). "Additionally, a non-toxic dose of DON has been found to exacerbate DSS-induced colitis through the JAK2/STAT3 signaling pathway, suggesting its association with IBD risk." (PMID 37368693, 2023). "In rats with 2, 4, 6-trinitrobenzene sulfonic acid (TNBS)-induced colitis, CP reduced the expression of proinflammatory cytokines and blocked the phosphorylation of STAT3 and JAK2, resulting in significant relief of colitis." (PMID 40078988, 2025). "Numerous studies have shown that JAK2/STAT3 pathway is an important pathway inflammation influence colitis." (PMID 38626146, 2024). "DSS-induced colitis was alleviated by Gegen Qinlian decoction, which was mediated by the suppression of IL-6/JAK2/STAT3 signaling." (PMID 39133435, 2024). "There was also an assumption that glucocorticosteroids followed by infliximab represented the best initial treatment for developing immune colitis versus other colitis targets (e.g., integrins, IL-23, and JAK2)." (PMID 38920743, 2024). "Knockout GNAI1 and GNAI3 in BMDSCs cells can induce phosphorylation of JAK2 and STAT3, promoting colitis-associated tumors in mice." (PMID 39695099, 2024). "Compared with the control group, colitis dramatically upregulated the expression of phospho-JAK2 and phospho-STAT3 in the colon tissues, while the UTI treatment markedly inhibited the phosphorylation of JAK2 and STAT3." (PMID 38397811, 2024). "Formononetin can reduce the expression of IL-6 to alleviate colitis symptoms in mice and inhibit JAK2/STAT3 signaling pathway transduction to protect against cerebral ischemia reperfusion injury." (PMID 39318778, 2024). "We also found that NFκB signaling components were elevated in the model mice, as well as the protein expression of JAK2, p-Stat3/Stat3, and IL-6, suggesting increased colitis in the model group." (PMID 38004214, 2023). "In future, we will try to construct JAK2-knock down mice to study the effects of arbutin on mice colitis." (PMID 34594215, 2021). "In this study, we demonstrated that DOK3 plays a protective role in experimental colitis by restraining JAK2/STAT3 signaling in colonic neutrophils in response to commensal microbes." (PMID 34743196, 2021). "In this study, arbutin was found to significantly alleviate the symptoms of colitis by inhibiting the activity of JAK2." (PMID 34594215, 2021). "The effects of arbutin treatment on colitis were considerably inhibited by the JAK2 inhibitor AG490." (PMID 34594215, 2021). "The study aimed to investigate the effects and mechanisms of regulating JAK2 by arbutin on colitis in mice." (PMID 34594215, 2021). "AG490, a type of JAK2 inhibitor, was also used to elucidate the role of JAK2 in the treatment of colitis." (PMID 34594215, 2021). "The goal of the present study was to investigate the effects of TAK-242 on the gut microbiota and the TLR4/JAK2/STAT3 signaling pathway in mice with dextran sulfate sodium (DSS)-induced colitis." (PMID 32762699, 2020). "Treatment with different doses of TAK-242 in DSS-induced colitis mice significantly enhanced the expression of phosphorylated JAK2 and STAT3." (PMID 32762699, 2020). "JAK2 and STAT3 were upregulated in DSS-induced colitis tissue, while phosphorylated JAK2 and STAT3 were significantly downregulated." (PMID 32762699, 2020). "The results provided further evidences of the effects of CP on suppression of colitis and indicated the key role of IL-6/JAK2/STAT3 pathway as relevant targets of CP." (PMID 30042683, 2018).
colitis (continued). "The relative pp65, TLR4, and p-JAK2 levels in TNBS-induced colitis rats were diminished significantly after treatment of HP, MP, and LP." (PMID 30042683, 2018). "An attenuated trend of the expression of p65, pp65, TLR4, STAT3, p-STAT3, JAK2 in TNBS-induced colitis rats was observed in the groups treated with CP." (PMID 30042683, 2018). "TLR4/NF-κB and IL-6/JAK2/STAT3 signal pathways were investigated to evaluate the alleviation of CP on the TNBS-induced colitis." (PMID 30042683, 2018). "Compared with the normal group, mRNA levels of TLR4, NF-κB, IL-6, STAT3, and JAK2 in colitis rats remarkably increased (P < 0.001, P < 0.01)." (PMID 30042683, 2018). "In colitis rats, the observed up-regulation of pro-inflammatory cytokines including IL-6 was ameliorated by CP, meanwhile, phosphorylation of Stat3 and JAK2 was blocked." (PMID 30042683, 2018). "Meanwhile, the ratio of p-JAK2/JAK2 was decreased after mice with experimental colitis were treated for 7 days." (PMID 27932984, 2016). "It has also been reported that ginseng polysaccharides could improve the DSS-induced colitis by inhibiting the JAK2/STAT1/NLPR3 inflammasome-signaling pathway in mice, as well as enhance ginsenoside Rb1 absorption and affect gut microbial metabolism." (PMID 35327312, 2022). "It has been reported Panax ginseng polysaccharides (GPS) relieved the DAI, colon length shortening, and pathological changes in colonic tissue in mice with colitis, while adjusting oxidative level and inflammatory cytokines through inhibiting the JAK2/STAT1/NLRP3 pathway." (PMID 35327312, 2022). "High expression of phosphorylated JAK2 in colitis was significantly reversed by arbutin." (PMID 34594215, 2021). "Similarly, assessments on polysaccharides extracted from Aloe vera on UC-animal models depicted an improvement in colitis, via JAK2, p-JAK2, STAT-3, and p-STAT3 protein expression." (PMID 34912469, 2021). "The present study aimed to investigate the effect of regulating JAK2 by arbutin on colitis." (PMID 34594215, 2021). "In addition, SOCS3, a negative regulator of the JAK2 signal pathway, is upregulated as result of the aggravation of the JAK2 signal pathway in patients diagnosed with colitis." (PMID 34594215, 2021). "These outcomes indicated that arbutin could inhibit the apoptosis to maintain intestinal barrier function in colitis, and JAK2 maybe a potential target." (PMID 34594215, 2021). "EHLJ7 may induce intestinal flora to overexpress SCFA, especially butyric acid and then inhibit colitis inflammation through inhibition of JAK2/STAT3/SOCS1 pathway." (PMID 32038241, 2019). "Furthermore, MLKL attenuated colon inflammation and colitis tumorigenesis via suppression of inflammatory responses, inhibited intestinal tumorigenesis by suppressing the IL-6/JAK2/STAT3 pathway and promoted cellular differentiation in myeloid leukemia by facilitating the release of G-CSF." (PMID 36828808, 2023). "The main finding of our study was the observed reduction in JAK2/STAT3 phosphorylation after MN treatment, indicating that inhibition of the JAK and STAT pathways may be involved in MN treatment of colitis, which is associated with pro-inflammatory cytokine gene expression." (PMID 36312760, 2022). "In this study, it was observed that CdtB can up-regulate Jak2/Stat3 phosphorylation, suggesting that the promotion of Jak/Stat pathway may be involved in the effect of H. hepaticus CdtB on colitis, which is related to the expression of proinflammatory cytokine-related genes." (PMID 33777833, 2021). "The mechanism for this resistance to colitis may be attributable to increased IL-22/JAK2/STAT3 signaling, since recent studies indicate that activation of STAT3 within the intestinal epithelium plays an important role in mucosal tissue repair through secretion of IL-22 from innate immune cells." (PMID 22675454, 2012).